SHH (sonic hedgehog signaling molecule)
Diseases named in the same sentence as SHH in open-access papers (continued):
Sharing a sentence is not in itself a finding about the gene and the disease.
medulloblastoma (continued). "Suppressor of fused (SUFU) is widely regarded as a key negative regulator of the sonic hedgehog (SHH) morphogenic pathway and a known tumor suppressor of medulloblastoma (MB)." (PMID 38358805, 2024). "Aberrant activation of sonic hedgehog (SHH) signaling and its effector transcriptional factor GLI1 are essential for oncogenesis of SHH-dependent medulloblastoma (MBSHH) and basal cell carcinoma (BCC)." (PMID 38307877, 2024). "Conversely, deletions in the ATOH1 gene inhibit the SHH signaling pathway, thwarting medulloblastoma development (OMIM 601461)." (PMID 39022728, 2024). "The SHH signalling pathway plays a critical role in the pathogenesis of several CNS tumours, including gliomas, medulloblastomas and others." (PMID 39568072, 2024). "The RE1 silencing transcription factor (REST) is a driver of sonic hedgehog (SHH) medulloblastoma genesis." (PMID 38866867, 2024). "There were statistically significant differences in sex by medulloblastoma subgroups (chi-squared p-value=0.00004): Group 3 (n=144; 65% male), Group 4 (n=326; 67% male), SHH (n=223; 57% male) and WNT (n=70; 41% male)." (PMID 37035203, 2023). "Future studies should aim to characterize the effects of targeted therapy on the different transcriptional metaprograms of SHH-activated medulloblastoma and stratify those results according to age." (PMID 37568705, 2023). "To date, several studies on genomic events underlying medulloblastoma (MB) biology have expanded our understanding of this tumour entity and led to its division into four groups—WNT, SHH, group 3 (G3) and group 4 (G4)." (PMID 37501103, 2023). "The SHh signaling pathway, which is continuously activated due to inactivation mutations in the PTCH1 gene, is commonly observed in basal cell carcinoma and medulloblastoma." (PMID 37533228, 2023). "The CDK7 inhibitor, TZH1, has shown significant potency in suppressing the SHH-mediated proliferation of medulloblastoma cells, including those that are resistant to SMO inhibitors." (PMID 37568705, 2023). "Not only that, but also the crosstalk between SHH and other oncogenic pathways that are commonly overactivated in medulloblastoma, such as PI3K/mTOR and RAS/REF/MEK, can play a significant role in evading SMO inhibition." (PMID 37568705, 2023). "The SHH subgroup typically displays deregulation of the SHH signaling pathway and represents approximately one-third of childhood patients with medulloblastomas." (PMID 38136401, 2023). "Herein, cyclopamine is the earliest SMO inhibitor investigated in the context of SHH-activated medulloblastoma, and it acts by binding to the transmembrane portion of the receptor." (PMID 37568705, 2023). "Another notable distinction observed in our cohort was the higher frequency of 46% for SHH-activated medulloblastomas." (PMID 37746264, 2023). "Sonic hedgehog medulloblastoma (SHH-MB) accounts for 25–30% of all MBs, and conventional therapy results in severe long-term side effects." (PMID 37240259, 2023). "TGF-β secretion has been documented in medulloblastomas and TGF-β pathway activity is potentially a predictor of survival in SHH-driven medulloblastomas." (PMID 37035203, 2023). "In particular, in a subset of Sonic hedgehog (SHH)-dependent medulloblastomas, the presence of PC is necessary for cancer maintenance." (PMID 37958846, 2023). "Initially, medulloblastoma was divided by transcriptional profiling into SHH, WNT, Group3 (MBGrp3) and Group4 (MBGrp4); each has now been further subdivided into subgroups by DNA methylation patterns." (PMID 37021628, 2023). "Driver mutations and inhibitors that play a role in tumor proliferation have been identified in WNT and SHH altered medulloblastoma with further characterization needed to better understand group 3 and 4 tumors that tend to have the worst outcomes." (PMID 37509034, 2023). "The SHH pathway plays a critical role in the development of the cerebellum and is frequently dysregulated in medulloblastoma." (PMID 37568705, 2023).
medulloblastoma (continued). "Jude is investing this in combination with adjuvant chemotherapy for SHH-activated medulloblastoma in children (NCT01878617)." (PMID 37509034, 2023). "The signaling deregulation of sonic hedgehog (SHH) is one of the molecular signatures of medulloblastoma (MB), the most common malignant pediatric brain tumor." (PMID 37240259, 2023). "Mutations in genes involved in histone acetylation – including CREBBP – are overrepresented in Sonic hedgehog (SHH)-activated medulloblastoma." (PMID 37407554, 2023). "GLI2 activation is also a key driver of SHH subset of medulloblastomas, which originate from granule cell progenitors." (PMID 37943875, 2023). "In a similar fashion, sonidegib has shown good safety and efficacy in pediatric and adult patients with progressive or refractory SHH-activated medulloblastomas during a phase I/II trial (NCT01125800)." (PMID 37568705, 2023). "In this review, we examined the most relevant studies on the topic, taking advantage of our recent publication on the role of NBS1 as both a haploinsufficient tumor suppressor and an essential gene in SHH-medulloblastoma." (PMID 37509263, 2023). "SHH-type medulloblastoma is often accompanied by abnormal activation of the SHH signaling pathway, and studies have shown that abnormal activation of this pathway often affects normal cerebellar development." (PMID 37821528, 2023). "Vismodegib is a small molecule inhibitor of the SHH pathway which has shown some efficacy against SHH-activated medulloblastoma in adults." (PMID 37509034, 2023). "Recurrent epigenetic alterations in SHH-activated medulloblastoma have been described in MLL2/KMT2D and MLL3/KMT2C, two lysine methyltransferases associated with an active chromatin state and the H3K4me2/3 status." (PMID 37568705, 2023). "To conclude, in our sex-stratified analysis of methylation differences within medulloblastoma subgroups, we identified sex-DMPs that varied by subgroup with SHH having the highest number of DMPs." (PMID 37035203, 2023). "For example, compared with SHH-medulloblastoma, WNT-medulloblastoma has a more permeable vasculature which enables the accumulation of chemotherapeutic drugs within the tumor lesion." (PMID 37705736, 2023). "Gorlin syndrome presents with a constellation of skin tumors, craniofacial changes, and an increased incidence of SHH-activated medulloblastomas." (PMID 37943476, 2023). "Promising effects of the drug have been documented in the context of prostate cancer, gastric cancer, and hepatocellular carcinoma, and it is, therefore, worth being further investigated in the setting of SHH-activated medulloblastoma." (PMID 37568705, 2023). "It has been reported that SHH activation in medulloblastoma cells induces the expression of SNAI1, consequently activating the proto-oncogene N-MYC to induce cellular proliferation and transformation." (PMID 35344158, 2022). "Adult SHH-medulloblastoma have frequent upstream pathway alterations (PTCH1 and SMO mutations), but infrequent downstream alterations (SUFU, MYCN amplifications)." (PMID 36249063, 2022). "One-third of medulloblastomas evolve from an aberrant activation of the sonic hedgehog (SHH) signaling pathway." (PMID 36012581, 2022). "Whereas SHH medulloblastoma is characterized by an overall deregulation of the SHH signaling pathway, there are also abnormalities specific to patient age." (PMID 35535520, 2022). "Sonic hedgehog (SHH) medulloblastoma originates from the cerebellar granule neuron progenitor (CGNP) lineage, which depends on Hedgehog signaling for its perinatal expansion." (PMID 35535520, 2022). "This interaction can be significantly disrupted with JQ1 treatment, providing a biological rationale for BET inhibition in SHH-driven medulloblastoma." (PMID 35745584, 2022).
medulloblastoma (continued). "Still, recurrent mutations of DDX3X have been reported in medulloblastoma (a common childhood hindbrain tumor), mainly in wingless-type MMTV integration site family (WNT)-activated medulloblastomas and sonic hedgehog (SHH)-activated medulloblastomas." (PMID 35874614, 2022). "HELLS is overexpressed in SHH human and murine medulloblastoma tumors, and its expression its activated by the SHH pathway, specifically by YAP1, which acts downstream of Smoothened." (PMID 36012581, 2022). "Of the four known molecular subgroups in medulloblastoma–SHH, WNT, Group 3, and Group 4—both the POLE‐mutated cases belonged to the SHH subgroup." (PMID 34351088, 2022). "The sonic hedgehog (SHH) pathway is altered in a significant proportion of older patients with medulloblastoma." (PMID 35053576, 2022). "From analyzing the results and current statuses of clinical trials associated with functional medulloblastoma treatment, it is plausible to state that SHH-subtypes are the most targeted; recurrent medulloblastoma patients are also a target." (PMID 35481313, 2022). "More recent studies, however, have shown that SHH medulloblastomas can arise from either transformed neural stem cells (NSC) in the neuroepithelium or CGPs in the external granule layer (EGL) when the SHH pathway is aberrantly activated." (PMID 36688010, 2022). "The investigated therapies tend to target sonic hedgehog (SHH)-subtype medulloblastomas, but there is a necessity for group 3 subtype and group 4 subtype to be targeted as well." (PMID 35481313, 2022). "Together, these data show that the age of the medulloblastoma cell-of-origin determines the extent of the response to SHH pathway activation, and as a consequence has an impact on SHH drug sensitivity." (PMID 35535520, 2022). "For example, to address resistance to SMOis in patients with BCC and medulloblastomas, second-line therapies inhibiting downstream activators of the SHH pathway, such as GLI, are being investigated." (PMID 36688010, 2022). "In particular, we found that primary cilium expression was low across young CGNPs and young medulloblastoma patients, which was somewhat unexpected given the importance of primary cilia for SHH pathway activity." (PMID 35535520, 2022). "Among medulloblastoma group, majority were group 4 (55%) followed by SHH (20%) while WNT and unclassified constituted 10% each and one patient was with group 3." (PMID 35773667, 2022). "Despite recent progress in the establishment of in vitro and in vivo medulloblastoma models, current models mainly cover SHH and Group 3 medulloblastoma and models for WNT and Group 4 are clearly underrepresented." (PMID 36497454, 2022). "Relevant biomarkers are collected for all tumour types, including (but not limited to) hormone receptor/HER2 status for breast cancer metastases, WNT and SHH activation for medulloblastoma, and mitotic figures for meningioma." (PMID 35655179, 2022).
medulloblastoma (continued). "We focused on medulloblastoma, which was classified into four subtypes (Group 3, Group 4, SHH, and WNT) in a previous study." (PMID 35603200, 2022). "Wingless (WNT), sonic hedgehog (SHH), group 3 (G3), as well as group 4 (G4) medulloblastoma are four primary molecularly and histopathologically different categories of medulloblastoma." (PMID 35574421, 2022). "More recently, rare medulloblastomas harboring dual activation of both SHH and WNT pathways have been described." (PMID 35266242, 2022). "Both genotypes developed medulloblastoma with 100% penetrance and in hGFAP-Cre/PtcloxP/loxP where SHH was hyperactivated throughout the brain, tumors developed only in the cerebellum." (PMID 34021242, 2021). "In medulloblastoma in general, four molecular variants are of great importance: WNT, SHH, group 3, and group 4." (PMID 33497354, 2021). "SHH-subgroup medulloblastomas are grouped together because they show similar patterns of gene expression in bulk transcriptomic studies, indicating SHH pathway activation." (PMID 34021242, 2021). "Specifically, interfering with MAPK15 functions reduces HH signaling and assembly of primary cilia both in immortalized NIH3T3 mouse fibroblasts and in transformed human medulloblastoma cells belonging to the SHH-driven subtype." (PMID 34638386, 2021). "A study with sonidegib in children and adults showed a tumor response in SHH-activated medulloblastomas, however, in children the drug was discontinued early due to its inhibitory effect on skeletal growth plates." (PMID 33808415, 2021). "The recently published MEVITEM trial evaluated vismodegib, another SMO inhibitor, plus temozolomide in immunohistochemically defined, recurrent, SHH-driven adult medulloblastoma." (PMID 34298664, 2021). "The SHH group, found in 30% of all medulloblastoma cases, is vital for the proliferation of cerebellar granule neuron precursors (GNPs); its constitutive activation triggers medulloblastoma." (PMID 34577571, 2021). "To date, the majority of pediatric brain tumor GEMMs are SHH-activated medulloblastoma, which are generated by modifying SHH signaling genes, such as PTCH, SMO, or SUFU." (PMID 33869004, 2021). "Authors found three subtypes of adult medulloblastoma, WNT, SHH and Group D/4, whereas Group 3 medulloblastomas are extremely rare in adult patients." (PMID 33497354, 2021). "LSD1 expression is prominently increased among WNT, SHH, and group 3 compared to group 4 medulloblastoma." (PMID 34066495, 2021). "About 60% of adult medulloblastomas present SHH pathway activation, which correlates with an intermediate prognosis." (PMID 34360713, 2021). "During the processes of tumorigenesis, ATOH1 is required to attain GCP identity, which serves as a critical event for the formation of SHH-induced medulloblastomas." (PMID 34012965, 2021). "Concordantly, SOX2 expression is higher in SHH-activated medulloblastomas than it is in other medulloblastoma subtypes with SOX2 activity serving as a regulator of stemness in these tumors." (PMID 34012965, 2021). "The EPC2–GULP1 fusion transcript is medulloblastoma-specific occurring in the SHH and WNT medulloblastoma subgroup." (PMID 34830991, 2021). "Genetic counselling should be provided for families with young medulloblastoma patients with SHH activation." (PMID 34888241, 2021).
medulloblastoma (continued). "A recent observational study of 111 medulloblastoma patients revealed a predictive accuracy of 95% for the SHH-activated group, 78% for group 4, 56% for group 3, and 41% for the WNT-activated group." (PMID 33822292, 2021). "This study serves to further elucidate the role of the stromal microenvironment in SHH-subgroup medulloblastoma and identify novel treatment possibilities for this challenging disease." (PMID 34667228, 2021). "The presence of many SHH-related alterations in these tumors has led to the classification of a medulloblastoma subtypes including the SHH-activated group." (PMID 34012965, 2021). "Dysregulation and overactivation of SHH signaling within GCPs is therefore thought to be responsible for medulloblastoma development and progression." (PMID 34012965, 2021). "The combination of low doses of MK-8776 plus olaparib efficiently inhibited also the growth of SHH-driven medulloblastoma in vitro and in vivo, confirming its efficacy in a different MYCN-driven tumor model." (PMID 34508175, 2021). "This has been shown to hold true in SHH-medulloblastoma as well, wherein the transition is proposed to be mediated by VEGFA-NPR2 signalling." (PMID 34667228, 2021). "When exogenous SHH proteins were added to the cultures, there was an increase in medulloblastoma cell proliferation." (PMID 34436033, 2021). "Transforming growth factor beta (TGF-B) signaling is known to antagonize the SHH pathway in medulloblastoma and has been shown to modulate invasiveness in a context-dependent fashion." (PMID 34667228, 2021). "Only two of them (RAP1A–TMIGD3 and ZSWIM5P2–MEIS3) occurred in both the WNT and SHH subtype as well as in group 3 and group 4 medulloblastoma." (PMID 34830991, 2021). "We subsequently investigated phospho-CREB expression in the putative cell-of-origin for SHH and Group 3 medulloblastoma, which is the CGNP14,16,17." (PMID 34373489, 2021). "For instance, a phase II trial on using a sonic hedgehog (SHH) inhibitor in children with SHH medulloblastoma was terminated because of the induction of widespread growth plate fusions." (PMID 33658498, 2021). "G-Smo and M-Smo tumors both showed transcriptomic profiles in microarray studies that were consistent with SHH-subgroup medulloblastoma." (PMID 34021242, 2021). "We analyzed 30 medulloblastoma samples for which SHH, WNT, group 3, and group 4 subgroups and subtypes within each subgroup had been using bulk transcriptomic and methylomic analysis according to published criteria." (PMID 34021242, 2021). "Between March 2011 and December 2019, 8 children, 4 females, and 4 males, received a SMOi for a medulloblastoma recurrence or progression with SHH pathway activation at Gustave Roussy." (PMID 34409296, 2021). "In these studies, SHH-driven medulloblastomas triggered early, in stem cells or later, in progenitor cells, show overall similarities but also specific differences." (PMID 34021242, 2021). "In both medulloblastoma and glioma cells, PAX6 expression is controlled by SHH-GLI signaling events: GLI1 activates PAX6 expression in medulloblastomas but suppresses it in gliomas." (PMID 34012965, 2021). "All SHH activated medulloblastoma patients younger than 4 years of age at diagnosis – especially DMB and MBEN - should be evaluated for Gorlin syndrome and systematically undergo specific genetic testing." (PMID 34888241, 2021). "Despite sharing a common oncogenic pathway, patients with SHH-subgroup medulloblastomas show different responses to treatment, with ~20% developing incurable recurrence." (PMID 34021242, 2021). "In medulloblastoma, one can observe that the activation of the SHH signaling pathway is connected with DNMT1 overexpression." (PMID 34066495, 2021). "SHH-activated medulloblastoma is highly heterogeneous and many key molecules in the SHH signaling pathway such as SUFU, smoothened (SMO), PTCH1, GLI1 and GLI2 have been dysregulated in this subgroup." (PMID 33869004, 2021).